SMIM11 (small integral membrane protein 11)
Synonyms: C21orf51; FAM165B; SMIM11A; SMIM11B
Tractability: Antibody: UniProt predicts a signal peptide or a membrane-spanning region. PROTAC: ubiquitination databases record sites on it.
Gene: Protein-coding gene on chromosome 21 (34,375,131 to 34,416,961, forward strand). Ensembl gene ENSG00000205670.
Subcellular location: Membrane
Subcellular location (Human Protein Atlas): Focal adhesion sites
Gene Ontology:
Molecular function: protein binding
Cellular component: membrane
Homologues: Orthologues: dog SMIM11 (95% identical), pig SMIM11 (90% identical), guinea pig SMIM11 (79% identical), mouse Smim11 (79% identical), rat Smim11 (79% identical).
Diseases named in the same sentence as SMIM11 in open-access papers:
SMIM11 is named in the same sentence as 1 disease in open-access papers, as found by Europe PMC text mining. Sharing a sentence is not in itself a finding about the gene and the disease. The quoted sentences say what the papers report.
muscular dystrophy (1 paper, 2021). Muscular dystrophy (MD) refers to a group of more than 30 genetic diseases characterized by progressive weakness and degeneration of the skeletal muscles that control movement. "Among them, two examples were selected to illustrate age-related differential exon usage: SMIM11A mRNA (Small Integral Membrane Protein 11A, of unknown function) and RXYLT1 mRNA (Ribitol Xylosyltransferase 1, associated with Walker–Wahlburg syndrome and muscular dystrophy–dystroglycanopathy)." (PMID 33795677, 2021).